VPS25 (vacuolar protein sorting 25 homolog)
Description:
Component of the ESCRT-II complex (endosomal sorting complex required for transport II), which is required for multivesicular body (MVB) formation and sorting of endosomal cargo proteins into MVBs. The MVB pathway mediates delivery of transmembrane proteins into the lumen of the lysosome for degradation. The ESCRT-II complex is probably involved in the recruitment of the ESCRT-III complex. The ESCRT-II complex may also play a role in transcription regulation, possibly via its interaction with ELL. The ESCRT-II complex may be involved in facilitating the budding of certain RNA viruses.
Synonyms: DERP9; EAP20; MGC10540; FAP20
Tractability: Antibody: UniProt places it where antibodies can reach, with medium confidence. PROTAC: ubiquitination databases record sites on it; its protein half-life has been measured.
Gene: Protein-coding gene on chromosome 17 (42,773,449 to 42,779,599, forward strand). Ensembl gene ENSG00000131475.
Subcellular location: Cytoplasm; Endosome membrane; Nucleus, nucleoplasm
Subcellular location (Human Protein Atlas): Vesicles
Pathways (Reactome):
Disease: HCMV Late Events
Vesicle-mediated transport: Endosomal Sorting Complex Required For Transport (ESCRT)
Gene Ontology:
Molecular function: protein binding; protein homodimerization activity; structural molecule activity
Biological process: negative regulation of epidermal growth factor-activated receptor activity; macroautophagy; membrane fission; multivesicular body assembly; protein transport to vacuole involved in ubiquitin-dependent protein catabolic process via the multivesicular body sorting pathway; multivesicular body sorting pathway
Cellular component: cytoplasm; cytosol; endosome membrane; ESCRT II complex; extracellular exosome; nucleus; nucleoplasm
Genetic constraint (gnomAD): Loss-of-function variants: 19 observed, 27.25 expected, observed/expected ratio (o/e) 0.7, 90% interval 0.49 to 1.02. The upper end of that interval is the gene's LOEUF score, 1.02, which puts it in group 4 of 6, group 1 being the genes least tolerant of losing a copy. Missense variants: 153 observed, 220.19 expected, observed/expected ratio (o/e) 0.69, 90% interval 0.61 to 0.8. Synonymous variants: 98 observed, 91.56 expected, observed/expected ratio (o/e) 1.07, 90% interval 0.91 to 1.27.
Homologues: Orthologues: chimpanzee VPS25 (100% identical), dog VPS25 (99% identical), mouse Vps25 (99% identical), pig VPS25 (99% identical), rat Vps25 (98% identical), rabbit VPS25 (98% identical), guinea pig VPS25 (97% identical), zebrafish vps25 (77% identical), tropical clawed frog vps25 (76% identical), macaque VPS25 (69% identical), Caenorhabditis elegans vps-25 (43% identical), Drosophila melanogaster Vps25 (42% identical).